IL7 (interleukin 7)
Diseases named in the same sentence as IL7 in open-access papers (continued):
Sharing a sentence is not in itself a finding about the gene and the disease.
Insulin resistance (8 papers, 2010 to 2024). Increased resistance towards insulin, that is, diminished effectiveness of insulin in reducing blood glucose levels. "Previous work has shown that IL-7 overexpression in mouse models is associated with glucose and insulin resistance." (PMID 36980567, 2023). "Here, we first show that transgenic mice overexpressing IL-7 have reduced adipose tissue mass associated with glucose and insulin resistance." (PMID 22768283, 2012). "Moreover fasting plasma levels of IL-7 was lately associated with insulin resistance in obese women with prediabetes." (PMID 27611669, 2016). "Indeed, constitutive IL-7 over-expression leads to glucose intolerance and insulin resistance, traits that are commonly associated with lipodystrophy in both animals and humans." (PMID 22768283, 2012). "This suggests that IL-7 overexpression impairs the adipocyte differentiation process, thereby contributing to the development of insulin resistance in lipodystrophy-like transgenic animals." (PMID 22768283, 2012). "All these data suggest that IL-7 could possibly be over secreted under inflammation and insulin resistance conditions." (PMID 27611669, 2016). "Moreover, our results reinforce the contribution of immune cells in insulin resistance in which IL-7 may play some important role." (PMID 22768283, 2012). "IL-7 was also shown increased in obese diabetic patients compared to obese non-diabetic ones and related to insulin resistance." (PMID 27611669, 2016).
latent infection (8 papers, 2011 to 2020). "Having found that this was not the case, we then considered the possibility that the CD127+ cells preferentially undergo latent infection, particularly since IL7, the ligand for CD127, has been implicated in driving persistence of latently-infected cells in vivo via homeostatic proliferation." (PMID 32353080, 2020). "TCM cells were purified from healthy donors and subjected to IL-7-based in vitro latent infection with HIV-1 strains NL4.3-wt and BaL." (PMID 28539614, 2017). "CCL19, CCL21, IL-7, and IL-15 are known to promote latent infection in resting CD4+ T-cells." (PMID 29997630, 2018). "The EGFP- cells were then activated with anti-CD3/anti-CD28/IL-7 to reactivate latent infection." (PMID 27383184, 2016). "We also quantified post-integration latent infection by stimulating T-cells with anti CD3/CD28 and IL-7 stimulation in the presence of L8." (PMID 26362311, 2015). "Based on the ratio of latently infected to productively infected cells, IL-7–treated resting CD4+ T cells and activated CD4+ T cells also support more productive infection than latent infection." (PMID 26067822, 2015). "A latent infection was established using DHIV-GFP (day 7), and at day 14, cells were labeled with CPe670; cells were then treated with either IL-2 alone or IL-2+IL-7." (PMID 21998586, 2011). "Interestingly, the cytokine, IL-7, which increases permissibility of resting CD4+ T cells to productive HIV infection, also increased both productive and latent infection in resting CD4+ T cells in our study." (PMID 26067822, 2015). "While IL7 appears to promote HIV latency establishment in resting cells derived from blood, the tissue CD127+ Tm cells are poised to undergo latent infection in the absence of IL7, as IL7 was not added to our cultures during latency establishment and is only present in limited amounts in HLACs." (PMID 32353080, 2020).
liver fibrosis (8 papers, 2016 to 2024). "IPA analysis showed that genes downregulated in pWAT FB LXRα S196A were associated with inflammation (Primary immunodeficiency, and IL7 signaling); hepatic fibrosis signaling; cells polarization, survival, and proliferation." (PMID 33772096, 2021). "While knockout of Atg5, a key player in autophagy, has been proven to aggravate liver fibrosis, IL-7 has been confirmed to promote liver injury and inflammation by suppressing the autophagy of KCs." (PMID 35656309, 2022). "In short-lasting HCV infection and low-rate liver fibrosis progression cases, the treatment with IL-7 was enough to restore T cell reactivity." (PMID 33802622, 2021). "In patients with an intermediate stage with either long-lasting disease or rapid hepatic fibrosis rate, the anti-PD-L1 plus IL-7 treatment rescue T cell reactivity." (PMID 33802622, 2021). "Individuals with higher scores of liver fibrosis (i.e. F3-F4 scores) produced significantly less Bcl-2 in response to IL-7 (10ng/ml) compared to those with lower degrees of fibrosis (i.e. F0-F2) (p = 0.02, unpaired Student’s t-test)." (PMID 27315061, 2016). "Production of Bcl-2 following IL-7 stimulation was also lower in HCV infection and inversely related to the degree of liver fibrosis." (PMID 27315061, 2016). "IL-7/IL-7R signaling inhibits Schistosoma japonicum egg antigen–triggered macrophage autophagy through amp-activated protein kinase (AMPK) signaling, thereby aggravating liver fibrosis in Schistosoma japonicum infection." (PMID 35656309, 2022).
Anxiety (7 papers, 2018 to 2025). Intense feelings of nervousness, tension, or panic often arise in response to interpersonal stresses. "IL-7 may play an important role in mediating anxiety in patients with chronic inflammatory conditions." (PMID 35098831, 2022).
B-cell lymphoma (7 papers, 2017 to 2023). "This fusion receptor converts immunosuppressive TGF-β signals into immune-activating IL-7 signals, effectively suppressing B-cell lymphoma recurrence." (PMID 38516299, 2023). "The importance of keeping IL-7R-mediated signaling under control is illustrated by studies showing that Il7 transgenic mice develop B cell lymphomas, and that IL-7 induces proliferation of human B-ALL cells." (PMID 34907175, 2021). "Along with the pivotal role in T-cell biology, IL-7/IL-7R pathway has been also shown to promote leukemogenesis in vivo, since T- and B-cell lymphomas develop in IL-7 transgenic mice." (PMID 28872614, 2017). "recently introduced a TGF-β-targeting switch receptor that can change TGF-β signaling into IL-7 signaling, and expression of the receptor improved tumor control in the CAR-T-based B-cell lymphoma suppression model." (PMID 37928546, 2023). "In the context of B-cell lymphoma, a promising strategy involves coexpressing CD19 CAR with a TGF-β/IL-7 fusion switch receptor." (PMID 38516299, 2023). "Here, we demonstrated an approach to inhibit recurrence of B cell lymphoma by co-expressing both a human anti-CD19-specific single-chain variable fragment (scFv) CAR (CD19 CAR) and a TGF-β/IL-7 chimeric switch receptor (tTRII-I7R) in T cells (CD19 CAR-tTRII-I7R-T cells)." (PMID 34445415, 2021).
Chronic colitis (7 papers, 2012 to 2025). A chronic inflammatory disease of the large intestine (colon, cecum and rectum). "IL-7 exacerbates chronic colitis in mice by inducing expansion of mucosal CD4+ IL-7Rhigh T cells." (PMID 28770173, 2017). "However, IL-7 exacerbates chronic colitis, with expansion of mucosal CD4+IL-7Rhigh T cells in mice." (PMID 27424033, 2016). "IL-7 activates IL-7 receptor α and induces proliferation and long-term survival of effector memory CD4+ T cells, leading to chronic colitis." (PMID 33597887, 2020).
lymph node metastasis (7 papers, 2007 to 2024). "Serum IL-7 was not correlated with cancer stage, the extension of the primary tumor, lymph-node metastasis, or distant metastasis." (PMID 31185636, 2019).
neuroblastoma (7 papers, 2014 to 2023). Neuroblastoma (NB) is the most common solid, extracranial childhood tumor. "Prasad's finding implicated IL7 within the Schwannian stroma of the neuroblastoma tumor architecture as having a paracrine signaling effect on neighboring neuroblasts which may provide the antiproliferative and differentiation signals postulated." (PMID 32963529, 2020). "Another ongoing clinical trial at Baylor College of Medicine investigated GD2-CAR-T cells modified with cytokine interleukin-7 (IL-7) to increase T cell survival for neuroblastoma (NCT03635632)." (PMID 36853475, 2023). "The cytokines IFN-γ, IL-2, IL-7, IL-12, IL-15, IL-18, IL-21, and IL-27, promoted neuroblastoma regression via enhancing the efficacy of effector cells, whereas VEGF, IL-6, and IL-10 induced neuroblastoma progression through their immunosuppressive activities." (PMID 33322408, 2020).
osteoarthritis (7 papers, 2008 to 2023). A noninflammatory degenerative joint disease occurring chiefly in older persons, characterized by degeneration of the articular cartilage, hypertrophy of bone at the margins and changes in the synovial membrane. "Although it has been linked with osteoarthritis, the role of IL-7 in this context is mainly detrimental, contributing to the wreckage of cartilage in various joint disorders, including OA." (PMID 38107476, 2023). "Elevated IL-7 enhances MMP-13 production in osteoarthritis patients, which has a significant effect in degenerative diseases." (PMID 36186138, 2022). "It has been reported that IL-7 has comparable pathological characteristics in osteoarthritis and IVDD." (PMID 36186138, 2022). "In knee OA, IL-7 in synovial fluid was demonstrated to correlate positively with patient age, but was depressed in patients with severe osteoarthritis affecting multiple knee compartments." (PMID 35126358, 2021). "The underlying consensus depicts IL-7 more as a marker for osteoarthritis rather than a therapeutic avenue leveraged through exercise." (PMID 38107476, 2023). "Recent data from the Osteoarthritis Initiative cohort also indicates that significantly decreased levels of IL-7 are present in accelerated hand OA which progresses from minimal radiographic disease to end-stage over the course of 48 months (accepted abstract)." (PMID 35126358, 2021). "These novel findings indicate that IL-7 may contribute to cartilage destruction in joint diseases, including osteoarthritis." (PMID 18289383, 2008). "Notably, IL-7 levels spike in the synovial fluid (SF) of older individuals with varying OA severities; however, it diminishes in cases of severe compartment 3 osteoarthritis, presumably owing to the substantial damage to cartilage cells enmeshed in the affected tissue." (PMID 38107476, 2023). "This is because, IL-7 stimulates the secretion of S100A4, which has been verified to be elevated in osteoarthritis and upregulates the expressions of MMP13 by activating the JAK/STAT pathway." (PMID 36186138, 2022).
primary Sjögren’s syndrome (7 papers, 2013 to 2023). "An association between elevated IL-7 levels and Sjögren syndrome was observed in mice." (PMID 34199238, 2021). "An implication of IL-7 in Th17 differentiation has recently been proposed in primary Sjögren’s syndrome and in skin cancer although it remained to be explored in RA." (PMID 25533722, 2014). "Notably, Sjøgren’s Syndrome (SS) has been associated with overexpression of proinflammatory cytokines, including TNF-α, IL-7, IL-1β, IL-6, IL-10, IL-17, IL-18 and gamma-interferon (γ-IFN)." (PMID 29997338, 2018). "The other examples are CCL2, IL7, CXCR3, and CXCL12, which are found in scleritis, dry eye disease, glaucoma, dry eye disease, and Sjögren’s syndrome." (PMID 31810226, 2019).
sarcoidosis (7 papers, 2009 to 2023). Sarcoidosis is a multisystemic disorder of unknown cause characterized by the formation of immune granulomas in involved organs. "Elevated IL-7 serum levels have been described in patients with natural stone silicosis and sarcoidosis and are associated with the severity of coronavirus disease 19 (COVID-19)." (PMID 36675056, 2023). "Meanwhile, the “hsa04060: cytokine–cytokine receptor interaction’ pathway, including the CCL4, CSF1R, CXCR4, FLT1, and IL7 genes, could be highly associated with immune regulation and is strongly suspected to be involved in the pathogenesis of sarcoidosis." (PMID 35860586, 2022). "When ILD in SSc patients was compared with the ILD due to sarcoidosis, higher IL-8 levels in addition to higher IL-7 levels were detected." (PMID 19615053, 2009). "Therapies that stimulate cellular immunity (interleukin-2, interleukin-7) have not proven their efficacy and could on the contrary induce sarcoidosis flare." (PMID 34359324, 2021).
thymic atrophy (7 papers, 2010 to 2022). "IL-7 promotes lymphocyte survival and expansion but its expression declines with age-associated thymic atrophy." (PMID 35246776, 2022). "Cytokines like IL-7 present in breast milk are vital for development of the thymus and hence age related thymic atrophy is associated with low IL-7." (PMID 33397296, 2021). "A previous study has shown that age-related thymic atrophy is associated with decreased expression of interleukin-7 (IL-7)." (PMID 31179312, 2019). "Compared with their less active counterparts, the cyclists had significantly higher serum levels of the thymoprotective cytokine IL‐7 and lower IL‐6, which promotes thymic atrophy." (PMID 29517845, 2018). "It has been shown that IL-7 can reverse thymic atrophy in old animals, ensuring increased thymic output to replenish the peripheral T lymphocyte pool and improving immune responses." (PMID 20546588, 2010). "One striking feature of using IL-7 to reverse thymic atrophy was the importance of the quantity of IL-7 present in the thymus as shown by experiments in which three lines of transgenic mice were generated in which the IL-7 gene was placed under the control of an lcx promoter." (PMID 29416551, 2018).
breast tumor (6 papers, 2013 to 2023). "Upregulation of genes encoding IL-2 and IL-7 has been associated with some classes of breast tumors; these were also upregulated in mammary glands of 10-week HFD-fed mice." (PMID 24156623, 2013). "Intratumoral ablation of interleukin 7-expressing fibroblasts impaired breast tumor growth and reduced the clonogenic potential of cancer cells." (PMID 29632733, 2018). "We found that Il7-expressing CAFs promoted breast tumor growth and provided critical niches for maintenance of BC stemness." (PMID 29632733, 2018). "However, a previous study reported that intratumoral ablation of IL-7-expressing fibroblasts impairs breast tumor growth and reduces the clonogenic potential of cancer cells in a mouse model." (PMID 36672342, 2023). "In this study, we describe a hitherto unknown population of murine breast tumor-promoting fibroblasts that are characterized by Il7 promoter activity." (PMID 29632733, 2018). "In particular, Cxcl12 expression was strongly enhanced in interleukin 7-producing fibroblasts and cell type-specific genetic ablation and systemic pharmacological inhibition revealed that the CXCL12/CXCR4 axis impacts breast tumor cell stemness." (PMID 29632733, 2018).
Cirrhosis (6 papers, 2019 to 2024). A chronic disorder of the liver in which liver tissue becomes scarred and is partially replaced by regenerative nodules and fibrotic tissue resulting in loss of liver function. "Conversely, cirrhosis was linked to decreased levels of IL-2 receptor alpha (IL-2RA), IL-5, IL-7, and tumor necrosis factor beta (TNF-β)." (PMID 39457577, 2024).
leukopenia (6 papers, 2017 to 2025). "Among children who died following hospital discharge or required hospital re-admission, exaggerated production of interleukin-7 (IL-7) to all stimulation conditions, as well as leukopenia with reduced lymphocyte and monocyte counts, were observed." (PMID 35185860, 2021). "We have also shown that children who go on to have poor outcomes following hospitalization exhibit leukopenia at hospital discharge, as previously reported in well-resourced settings, and a trend towards heightened IL-7 response to all tested stimuli." (PMID 35185860, 2021). "It has been proposed that there is a correlation between leukopenia and changes in the immune milieu, with WBC counts being affected when changes in regulatory T-cell values and IL-7 are produced." (PMID 40890790, 2025). "The various stages of infection are characterized by high levels of inflammatory markers such as CRP, interleukins (IL-2, IL-6, IL-7), LDH, ferritin, lymphocytopenia, thrombocytopenia, leukopenia, elevated procalcitonin, D-dimer, prothrombin, fibrinogen, and others." (PMID 36982882, 2023).
macrophage activation syndrome (6 papers, 2020 to 2022). A complication of rheumatic disease that is caused by excessive activation and uncontrolled proliferation of T lymphocytes and well-differentiated macrophages. "SARS-CoV-2 increases interferon gamma, tumor necrosis factor-α, macrophage inflammatory protein-1 alpha, IL-2, IL-6, IL-7, IL-10, in patients, that show a form of secondary hemophagocytic lymphohistiocytosis or macrophage activation syndrome (sHLH/MAS)." (PMID 33494816, 2021). "Cytokine storm, defined as macrophage activation syndrome (MAS), is characterized by the release of multiple pro-inflammatory cytokines (IL-1β, IL-18, IL-6, IL-2, IL-7, TNF-α) and chemokines (CCL2, CCL3) from macrophages." (PMID 35008658, 2021). "The cytokine profile in these studies is comparable to that reported in cytokine release syndromes, such as macrophage activation syndrome, which is characterized by increased expression of cytokines (IL6, IL7, and TNF) and inflammatory chemokines (CCL2, CCL7, CXC-10, and CXCL-11)." (PMID 35145507, 2021). "Careful observation revealed that the excessive cytokines and chemokines activated by macrophages (i.e., IL-6, IL-7, TNF-α, CCL-2/MCP-1, CCL-3/MIP-1α) were similar to results previously found in hemophagocytic lymphohistocytosis (HLH) and macrophage activation syndrome (MAS)." (PMID 32922406, 2020).
periodontitis (6 papers, 2021 to 2025). An acute or chronic inflammatory process that affects the tissues that surround and support the teeth. "An unbalanced oral microbiome causes periodontitis and systemic disease by activating proinflammatory cytokines (IL‐1, IL‐7, IL‐10, IL‐17, IL‐8, TNF‐α, and MCP‐1) and neutrophils." (PMID 35578891, 2022). "IL-7 is also involved in periodontitis and orthodontic tooth movement by inhibiting the osteogenic differentiation of periodontal ligament stem cells through the mitogen-activated protein kinase pathway." (PMID 35280902, 2022). "The IL-7 expression has been found in both periodontitis and orthodontic tooth movement." (PMID 35280902, 2022). "In patients with periodontitis, the present study observed increased levels of pro-inflammatory factors IFN-γ, IL-1β, IL-2, IL-7, IL-21, and TNF-α, in addition to decreased levels of anti-inflammatory factors IL-5 in GCF of T2DM patients." (PMID 33417619, 2021). "Consequently, a high expression profile involving proinflammatory cytokines, IL‐1, IL‐7, IL‐10, IL‐17, IL‐8, TNF‐α, and monocyte chemoattractant protein‐1, were detected both in patients with periodontitis and those with COVID‐19." (PMID 35578891, 2022). "In patients with periodontitis, lower levels of pro-inflammatory factors IFN-γ, IL-1β, IL-2, IL-6, IL-7, IL-21, TNF-αand higher levels of anti-inflammatory factors IL-4 and IL-5 in gingival crevicular fluid in the Sp group were identified than those in the Dp group." (PMID 33417619, 2021). "As found in the present study, in T2DM patients with periodontitis, statins treatment reduced pro-inflammatory factors IFN-γ, IL-1β, IL-2, IL-6, IL-7, IL-21 and TNF-α levels in GCF, and enhanced anti-inflammatory factors IL-4 and IL-5 levels through the anti-inflammation and anti-oxidation effects." (PMID 33417619, 2021).